COL1A1 (collagen type I alpha 1 chain)
Diseases named in the same sentence as COL1A1 in open-access papers (continued):
Sharing a sentence is not in itself a finding about the gene and the disease.
liver fibrosis (continued). "Liver fibrosis was mostly not observed, as shown by the histological analyses with reduced mRNA levels of fibrogenic markers, including alpha smooth muscle actin (α-Sma), collagen type 1 alpha 1 (Col1a1), metalloprotein-3 (Mmp-3), and transforming growth factor beta (Tgfβ)." (PMID 36114279, 2022). "Furthermore, by measuring the protein levels of ECM markers, α-SMA and COL1A1, we revealed that capsaicin can attenuate, whereas TRPV1 KO mice could enhance, the effect of CCl4 on hepatic fibrosis, indicating that TRPV1 plays a protective role against CCl4-induced hepatic fibrosis." (PMID 35909891, 2022). "Indeed, nizatidine significantly reduced liver fibrosis measured by collagen proportionate area (CPA), α smooth muscle actin (αSMA) staining, quantitative analysis of hydroxyproline, and expression of genes mediating fibrogenesis (Acta2, Col1a1, Tgfb-1, and Timp1)." (PMID 34535664, 2021). "Doing so, we found that the deletion of adiponectin in HSCs accelerates the development of liver fibrosis as reflected by significant increases in SMA, Col1a1, Col3a1, Col4a4, and leptin, but not TGF-β expression in the liver." (PMID 39792554, 2025). "Although we noticed an upregulation of select acute phase response (e.g., Saa1, Saa2, and Orm2) and fibrosis genes (e.g., Col1a1 and Timp1) in livers of IXA4-treated DIO mice, IXA4 treatment did not increase liver fibrosis or the levels of multiple plasma cytokines." (PMID 35105890, 2022). "In mouse models, miR-29-3p could suppress the mRNA expression of COL1A1 and COL1A3 either with or without the induction by TGF-β1 and prevent S. japonicum-induced liver fibrosis." (PMID 32478052, 2020).
osteogenesis imperfecta (244 papers, 2004 to 2026). "For instance, COL1A1, the gene encoding the α1 chain of type I collagen, undergoes AS, and aberrant splicing events are associated with osteogenesis imperfecta." (PMID 41602857, 2026). "Osteogenesis imperfecta is usually associated with mutations in the genes encoding collagen type 1, COL1A1, and COL1A2." (PMID 40136761, 2025). "In Europe, approximately 85–90% of individuals with Osteogenesis Imperfecta (OI) have dominant pathogenic variants in the Col1a1 or Col1a2 genes whilst for Asian, especially Indian and Chinese cohorts, this ratio is much lower." (PMID 39908220, 2025). "Osteogenesis imperfecta (OI) is a genetic disorder resulting from gene mutationsencoding type 1 collagen, COL1A1, and/or COL1A2." (PMID 40630436, 2025). "Osteogenesis imperfecta or an increased fracture risk can also be caused by mutations in collagen genes COL1A1 and COL1A2." (PMID 41141281, 2025). "Mutations or polymorphisms in COL1A1 have been linked to various skeletal disorders, including osteoporosis and osteogenesis imperfecta." (PMID 41153339, 2025). "Mutations in COL1A1 can impair bone mineralization and cause bone diseases like osteogenesis imperfecta, underscoring its role in skeletal homeostasis." (PMID 40564415, 2025). "Osteogenesis imperfecta (OI) is an inheritable skeletal disorder characterized by bone fragility often caused by pathogenic variants in the COL1A1 gene." (PMID 39751826, 2025). "Research indicates that 90% of osteogenesis imperfecta (OI) cases result from pathogenic variants in the COL1A1 or COL1A2 genes, which encode the α1 and α2 chains of type I collagen, respectively." (PMID 40567897, 2025). "Mutations in COL1A1 are associated with osteogenesis imperfecta, and its polymorphisms can affect bone density and the development of osteogenesis imperfecta in 85–90% of cases." (PMID 41009461, 2025). "COL1A1 or COL1A2 mutations are the major cause of osteogenesis imperfecta (OI) with variable aortic and mitral valve disease and features of EDS." (PMID 38370698, 2024). "Numerous mutations in COL1A1 are associated with conditions such as osteoporosis and osteogenesis imperfecta." (PMID 39430588, 2024). "Osteogenesis imperfecta (OI) describes a group of inherited disorders, most often due to mutations in type I collagen genes (COL1A1, COL1A2) by an autosomal dominant inheritance." (PMID 39274387, 2024). "Osteogenesis imperfecta (OI) arises from a collagen type 1 defect due to several gene mutations, particularly COL1A1 and COL1A2." (PMID 39156321, 2024). "Mutation of COL1A1 results in disruption of the collagen I triple helix and causes inherited brittle bone disease osteogenesis imperfecta." (PMID 39139824, 2024). "Col1a1 is a hydrophilic protein that belongs to the collagen family and is closely associated with osteogenesis imperfecta, osteoporosis, and other skeletal injuries." (PMID 39125380, 2024). "Osteogenesis imperfecta type I in the majority of cases (~95%) is caused by mutations in the COL1A1 and COL1A2 genes; hence, in this study, we focused on sequencing analyses of those genes." (PMID 37895885, 2023). "Some studies describe combinations of DMD caused by deletions in the DMD gene with skeletal dysplasia: osteogenesis imperfecta (mutations in the COL1A1 gene) and pseudoachondroplasia (mutation in the COMP gene)." (PMID 37569734, 2023). "Osteogenesis imperfecta (OI) is a rare (~11 per 100,000), inherited systemic connective tissue disease largely caused by mutations in the COL1A1 or COL1A2 genes." (PMID 37623368, 2023). "Mutations in COL1A1 predispose to osteogenesis imperfecta, often also characterized by hearing loss." (PMID 36653343, 2023). "Osteogenesis imperfecta (OI) is a group of autosomal dominant genetic diseases associated with pathogenic variants of the COL1A1 and COL1A2 genes." (PMID 36831000, 2023).
osteogenesis imperfecta (continued). "Patients with certain forms of skeletal dysplasia such as osteogenesis imperfecta type I and IV manifested the heterozygous mutation of COL1A1/COLA2, shown as typical overstretching of the sutures." (PMID 36900016, 2023). "Nonetheless, genetic mutations in either the Col1a1 or Col1a2 genes in humans can result in various subtypes of osteogenesis imperfecta syndrome, commonly known as brittle bone disease." (PMID 37895821, 2023). "The aim of this study was to identify and analyze the expression profiles of miRNAs in osteogenesis imperfecta (OI) type I caused by mutations in the COL1A1 and COL1A2 genes." (PMID 37895885, 2023). "Most of them cause known monogenic disorders, such as osteogenesis imperfecta (COL1A1/COL1A2), pycnodysostosis (CTSK), X-linked osteoporosis (PLS3), osteopetrosis, X-linked hypophosphatemia (PHEX), and osteoporosis pseudoglioma syndrome (LRP5)." (PMID 37731773, 2023). "Our study finds a novel mutation site c.1922_1923 ins C in COL1A1 causing osteogenesis imperfecta/hearing loss." (PMID 37678008, 2023). "The mutation in COL1A1 gene, responsible for osteogenesis imperfecta, was successfully detected and a subsequent verification by Sanger sequencing of fetal and parental blood was performed." (PMID 36675662, 2022). "Osteogenesis imperfecta (OI) is a genetic disorder that affects bone strength as a result of mutation in the genes (COL1A1/COL1A2) responsible for collagen type I production." (PMID 36354587, 2022). "Nearly 85%-90% of osteogenesis imperfecta (OI) cases are caused by autosome dominant mutations of COL1A1 and COL1A2 genes, of which de novo mutations cover a large proportion, whereas their characteristics remain to be elucidated." (PMID 35909573, 2022). "Mutations in COL1A1 gene have been demonstrated to be responsible for the autosomal dominant form of osteogenesis imperfecta, with severe osteoporosis." (PMID 35937806, 2022). "In the majority of cases, osteogenesis imperfecta is caused by mutations in COL1A1 or COL1A2, which are genes that encode the two collagen type I alpha chains." (PMID 35804365, 2022). "Osteogenesis imperfecta was formerly thought to be a dominantly inherited disease produced by mutations in either of the type I collagen genes (COL1A1 and COL1A2)." (PMID 35399624, 2022). "Osteogenesis imperfecta (OI) is a disorder of connective tissue generally associated with dominantly inherited pathogenic variants in COL1A1 or COL1A2 genes." (PMID 36077325, 2022). "Pathogenic variants in COL1A1 are inherited in an autosomal dominant pattern and are causal for osteogenesis imperfecta type IV." (PMID 35918752, 2022). "This would be consistent with a defect in type I collagen deposition, as mutations in the COL1A1 gene are associated with osteogenesis imperfecta in both humans and zebrafish." (PMID 33944912, 2021). "The COL1A1 gene mutations have documented important roles in a range of diseases, with particular focus on bone and connective tissue diseases, in particular osteogenesis imperfecta and Ehlers–Danlos syndrome." (PMID 34572492, 2021). "Osteogenesis imperfecta is mostly caused by mutations in the COL1A1 (17q21.33) and COL1A2 (7q21.3) genes." (PMID 33920808, 2021). "The majority of osteogenesis imperfecta cases are autosomal dominant with underlying mutations in one of two genes encoding for type I collagen alpha chains, COL1A1 and COL1A22." (PMID 34036147, 2021). "Variation at intron eight donor site position +1 in collagen type I alpha 1 chain (COL1A1) causes osteogenesis imperfecta due to splicing defect." (PMID 32951567, 2021). "Osteogenesis imperfecta is commonly associated with mutations of the genes encoding for type I collagen (COL1A1/COL1A2)." (PMID 34036147, 2021). "Osteogenesis Imperfecta (OI) is a genetic disorder also known as ‘brittle bone disease’ Autosomal dominant mutations in the type I collagen coding genes (COL1A1 and COL1A2) affect the collagen structure in the majority of OI patients." (PMID 33743784, 2021).
osteogenesis imperfecta (continued). "Osteogenesis Imperfecta (OI) is a rare inheritable condition commonly caused by mutations in genes (COL1A1 and COL1A2) encoding collagen type I which is essential for healthy bone formation." (PMID 34569391, 2021). "Collagen-DyProQ has immediate applications in studying the synthesis, trafficking, secretion, and degradation of collagen-I caused by mutations in Col1a1 and Col1a2, such as osteogenesis imperfecta, the Ehlers-Danlos syndromes, and Caffey disease." (PMID 32927811, 2020). "Supporting our postulation, osteogenesis imperfecta, caused by heterozygous mutations in type 1 procollagen genes (COL1A1/COL1A2), is associated with communicating hydrocephalus." (PMID 32353054, 2020). "COL1A1 is often found in connective tissues (e.g., bone and tendon) and thus its mutation is most closely associated with osteogenic diseases, specifically osteogenesis imperfecta (Palomo, Vilaça & Lazaretti-Castro, 2017)." (PMID 33062455, 2020). "It has been demonstrated that osteogenesis imperfecta in humans, which is characterized by a tendency for bone fractures, is caused by mutations in either the COL1A1 or COL1A2 genes encoding type I collagen." (PMID 33029260, 2020). "The skeletal phenotype was associated with an autosomal dominantly inherited variant in COL1A1 which lead to a diagnosis of osteogenesis imperfecta." (PMID 32345347, 2020). "Mutations in COL1A1 usually cause osteogenesis imperfecta; and the reason for the differing phenotype in Caffey’s disease is not known – nor is it known why this condition settles down over time." (PMID 33193107, 2020). "Studies demonstrated that COL1A1 is linked to osteoporosis by regulating bone mineral density, and mutations in the COL1A1 gene can cause osteogenesis imperfecta." (PMID 33664707, 2020). "Osteogenesis imperfecta (OI) is a rare genetic disorder of the connective tissue and 90% of cases are due to dominant mutations in COL1A1 and COL1A2 genes." (PMID 30886339, 2019). "This increased secretion in response to PBA treatment in vivo is supported by data from other matrix diseases including Pierson syndrome due to laminin B2 mutations and Osteogenesis Imperfecta caused by a Col1a1 mutation." (PMID 30351356, 2019). "The most common form is osteogenesis imperfecta linked to mutations in COL1A1 and COL1A2, the two genes encoding type I collagen." (PMID 30858824, 2019). "After the discovery of the COL1A1 variant, the skeletal phenotype was diagnosed as a high bone mass form of osteogenesis imperfecta." (PMID 28173822, 2017). "Mutations in COL1A1 cause osteogenesis imperfecta leading to reduced bone mass and increased fracture." (PMID 28093083, 2017). "Osteogenesis imperfecta is a clinically heterogenous disease caused by defective collagen syntesis associated with a mutation in the COL1A1 or COL1A2 genes." (PMID 28904723, 2017). "Another collagen gene, COL1A1, was found to be associated with specific fibro-osseous lesions in the skull and jaw, as well as osteogenesis imperfecta and bone fragility." (PMID 27216912, 2016). "As mutations in COL1A1 gene are usually associated with Osteogenesis Imperfecta (OI) we performed a literature search to find possible reported cases with OI and associated glaucoma." (PMID 27484908, 2016). "Mutations in COL1A2 or its partner COL1A1 that encode type I collagen can cause dominant inheritance of osteogenesis imperfecta." (PMID 27711115, 2016). "The existence of this tissue specificity of RNA surveillance has been previously reported in other diseases, for example, osteogenesis imperfecta type I due to premature termination codon mutations COL1A1 gene." (PMID 25802402, 2015). "Osteogenesis imperfecta (OI), a congenital bone disorder, is caused by mutations in COL1A1 and COL1A2 genes, leading to deficiency of type I collagen." (PMID 26307460, 2015).
osteogenesis imperfecta (continued). "Osteogenesis Imperfecta (OI): OI, also known as brittle bone disease, is characterized by brittle bones that are prone to fracture and are caused by mutations in the COL1A1 or COL1A2 genes in the majority of cases." (PMID 25621177, 2014). "The majority of Osteogenesis Imperfecta (OI) cases are caused by mutations in one of the two genes, COL1A1 and COL1A2 encoding for the two chains that trimerize to form the procollagen 1 molecule." (PMID 24767406, 2014). "The Brtl/+ mouse is a knock-in model for osteogenesis imperfecta type IV in which a Gly349Cys substitution was introduced into one COL1A1 allele." (PMID 23802117, 2013). "Various collagens have been implicated in OA susceptibility and pathogenesis; mutations in col1a1 are associated with osteogenesis imperfecta both in the zebrafish and in humans." (PMID 23159952, 2013). "Osteogenesis imperfecta (OI) is a heritable form of bone fragility typically associated with a dominant COL1A1 or COL1A2 mutation." (PMID 19594296, 2010). "Osteogenesis imperfecta (OI) is a genetic disorder of bone fragility caused by defects in either the pro-α1(I) (COL1A1) or pro-α2(I) (COL1A2) genes encoding type I collagen." (PMID 23675157, 2009). "DGI type I is inherited with osteogenesis imperfecta and recent genetic studies have shown that mutations in the genes encoding collagen type 1, COL1A1 and COL1A2, underlie this condition." (PMID 19021896, 2008). "Osteogenesis imperfecta is an autosomal dominant condition usually resulting from mis-sense mutations affecting either of the two genes encoding type I collagen (COL1A1 and COL1A2)." (PMID 19021896, 2008). "Osteogenesis imperfecta (OI) most commonly results from heterozygous dominant COL1A1 or COL1A2 variants (~85% of classic cases), with additional dominant or recessive defects in collagen-processing genes producing a spectrum from mild (Type I) to perinatal lethal (Type II) disease." (PMID 41511357, 2026). "Osteogenesis imperfecta (OMIM #166200) is a genetic disorder primarily affecting connective tissues due to mutations in the Collagen Type I Alpha 1 Chain (COL1A1) and Collagen Type I Alpha 2 Chain (COL1A2) genes, which code for the α1 and α2 chains of type 1 collagen." (PMID 40004475, 2025). "Diagnosis requires differentiation from more common bone diseases: vitamin D–-deficient rickets (elevated ALP, metaphyseal fraying on x-ray), osteogenesis imperfecta (marked bone fragility, COL1A1/A2 genetic variants), and Marfan syndrome (aortic dilation, lens dislocation)." (PMID 40703321, 2025). "COL1A1 is linked to bone formation disorders (osteogenesis imperfecta and Ehlers-Danlos syndrome)." (PMID 39341500, 2024). "COL1A1 gene variants are associated with various musculoskeletal disorders, including intervertebral disc degeneration, osteoporosis, osteoarthritis, and osteogenesis imperfecta." (PMID 38787354, 2024). "Access to musculoskeletal services can address their needs, and the condition is often well managed through services that also have experience with osteogenesis imperfecta (OI) which is the most common manifestation of heterozygous pathogenic variants in COL1A1 or COL1A2." (PMID 39629459, 2024). "Polymorphisms in SP1 binding sites within the COL1A1 gene are significantly associated with clinical phenotypes, including collagen disease and osteogenesis imperfecta (OI), with mutations at the rs1800012 site linked to bone mineral density in women aged 45 years and older." (PMID 39596516, 2024). "Additionally, mutations in the COL1A1 gene have been identified as causal factors in monogenic connective tissue disorders such as osteogenesis imperfecta and Ehlers–Danlos syndrome." (PMID 38392197, 2024). "Notably, our enrichment analysis includes CREB3L1 and COL1A1, which, out of the top 10 genes, are associated with osteogenesis imperfecta type III (disorder)." (PMID 37508851, 2023). "•We report a novel mutation in COL1A1 causing osteogenesis imperfecta/hearing loss." (PMID 37678008, 2023).